RNF213 (ring finger protein 213)
Diseases named in the same sentence as RNF213 in open-access papers (continued):
Sharing a sentence is not in itself a finding about the gene and the disease.
viral infection (7 papers, 2021 to 2025). "Under the pathological condition where viral infection causes mitochondria destruction, RNF213 is upregulated and prohibits eNOS production by degrading NFAT1." (PMID 34381413, 2021). "Together, these findings strongly indicate that RNF213 functions as an antiviral protein, playing a critical role in safeguarding against viral infections." (PMID 37655297, 2023). "Knockdown or overexpression of RNF213 changed viral infection levels two to five fold, in contrast to Listeria where we observed up to 100,000 fold differences in bacterial load, especially in vivo, indicating a more pronounced antibacterial effect." (PMID 34599178, 2021). "Bacterial and viral infection may cause mitochondrial dysfunction and interferon (IFN) I generation, which may lead to increased RNF213 expression." (PMID 37273690, 2023). "Under pathological conditions, in which a viral infection may lead to destruction of mitochondria, RNF213 may be up-regulated and may inhibit the generation of eNOS through NFAT1 degradation." (PMID 37273690, 2023). "The high expression of several interferon-induced viral-response genes (e.g. Bst2, Ifitm3, Ube2l6, and Rnf213) in the control ‘interferon’ cluster might point to a state of general surveillance for viral infection at baseline." (PMID 34939923, 2021). "Thus, our unique Virotrap method revealed a functional link between ISG15 and RNF213, as well as an undiscovered role for RNF213 in host defense pathways to both bacterial and viral infections." (PMID 34599178, 2021). "Involvement of RNF213 in viral infection has just recently been reported." (PMID 34381413, 2021). "Overall, bacterial/viral infections could contribute to MA development in genetically susceptible subjects, although no RNF213 variant predisposed to MA was impaired during the LPS ubiquitylation ability." (PMID 35562882, 2022). "In summary, this study highlights the role of RNF213 in inhibiting KSHV and provides a novel idea for effective prevention and control of viral infection." (PMID 37655297, 2023).
artery stenosis (6 papers, 2022 to 2025). "Third, the prevalence of the RNF213 p.R4810K mutation in patients with intracranial artery stenosis, including MMD, varies with ethnicity." (PMID 39191959, 2025). "In sub-analyses, the association of RNF213 p.Arg4810Lys with intracranial artery stenosis/extracranial artery stenosis and maximum intima-media thickness were assessed." (PMID 39958261, 2025). "The RNF213 p.R4810K mutation may be the main cause of MMD intracranial artery stenosis and is more related to the MMD ischemic phenotype, whereas the rarer RNF213 p.A4399T mutation is more related to the MMD hemorrhagic phenotype." (PMID 34529262, 2022). "Ring finger protein 213 (RNF213) p.Arg4810Lys (c.14429G > A) is associated with intracranial artery stenosis; however, its association with extracranial artery stenosis remains unknown." (PMID 39958261, 2025).
ischemia (6 papers, 2012 to 2025). A hypoperfusion of the BLOOD through an organ or tissue caused by a PATHOLOGIC CONSTRICTION or obstruction of its BLOOD VESSELS, or an absence of BLOOD CIRCULATION. "The frequency of the mutant A allele of RNF213 R4810K was higher in the group with ischemia, than in the hemorrhage group." (PMID 23110205, 2012). "We found a significant difference in both the RNF213 A4399T genotype (P = 0.006) and allele frequency (OR = 2.8, 95% CI: 1.2–6.5, P = 0.014) between the hemorrhage and ischemia group." (PMID 23110205, 2012). "The allele frequency of RNF213 R4810K was significantly different between the ischemia and hemorrhage groups (OR = 5.4, 95% CI: 1.8–16.1, P = 0.001)." (PMID 23110205, 2012). "However, it remains unclear which RNF213 variants, apart from p.Arg4810Lys, are associated with the development of ischemia or hemorrhage, despite these previous reports." (PMID 37269436, 2024). "Rnf213-knockout mice exhibited no abnormalities in cervical or intracranial arteries or the circle of Willis; however, after internal carotid artery ligation–induced ischemia, the intimal and medial layers of the vessels were significantly thinned." (PMID 40485582, 2025).
aneurysm (5 papers, 2019 to 2024). Bulging or ballooning in an area of an artery secondary to arterial wall weakening. "In contrast, study of the association between aneurysms in French-Canadian patients and RNF213 demonstrated that the deleterious variant in AAA + motifs contributed to aneurysm formation based on the measurement of adenosine triphosphatase activity." (PMID 32686731, 2020). "We clarified the relationship between aneurysms and RNF213 by separating the aneurysm site and morphology." (PMID 34680863, 2021). "Through literature searches we found that the participant of ubiquitination related proteins (e.g. UCHL1, RNF213, UBR3, ARIH1) in pathogenesis of above-mentioned human aneurysm subtypes (ASH, AAA, CA, AA, AD) has been widely reported before." (PMID 34895131, 2021). "In addition, there was a negative view of the relationship between aneurysms and RNF213 itself." (PMID 34680863, 2021). "Hence, we aimed to investigate the role of RNF213 in patients with non-traumatic, non-infectious, non-neoplastic ICA “saccular” aneurysms (ICAN), diagnosed as ‘intracranial ICANs’ based on surgical findings in addition to multiple imaging methods." (PMID 34680863, 2021).
Cerebral ischemia (5 papers, 2018 to 2024). Restriction of arterial blood supply to the brain associated with insufficient oxygenation to support the metabolic requirements of the tissue. "And the co-localization of Rnf213 mRNA expression with TUNEL-positive neurons suggests that the Rnf213 gene plays a role in cell survival and cell death in neural tissue under cerebral ischemia, which is an underlying pathology of MMD31." (PMID 38467737, 2024). "This group later briefly clamped the rat common carotid artery to cause general cerebral ischemia and found that neuronal apoptosis in hippocampal CA1 region was associated with elevated Rnf213 mRNA, suggesting that RNF213 mediates apoptosis of hypoxic-ischemic neurons." (PMID 30671466, 2018). "This supports a role of RNF213 in brain ischemia, a symptom of MMD, but further studies are needed to understand the mechanism of RNF213 action in MMD." (PMID 29491882, 2018).
hemorrhage (5 papers, 2012 to 2025). Loss of blood from the vascular compartment to the exterior or into nonvascular body space as a result of rupture or severance of the blood vessels. "In the current study, the RNF213 p.R4810K mutation significantly increased the risk of cerebrovascular events (symptomatic infarction or hemorrhage) in MCAD in both patient-based and hemisphere-based analyses." (PMID 39191959, 2025). "When considering choroidal PA, a well-known risk factor for hemorrhage in MMD, there have only been a few subsequent reports from China regarding the association between choroidal PA and RNF213 variants." (PMID 37269436, 2024).
migraine (5 papers, 2019 to 2023). "The resulting subnetwork included 9 genes: migraine-associated genes APOE, LRP1, CARF, CTIF, RNF213, and ECM1; LAMA2, which is associated with vestibular anomalies in mice; and the neurodevelopment-associated genes MYO5A and KLC2." (PMID 37107589, 2023). "The majority of the identified variants were found in genes previously associated with migraine (LRP1, ECM1, CARF, CTIF, RNF213, APOE, SLC35D2), with two different rare LRP1 variants each identified in two unrelated children with vertigo." (PMID 37107589, 2023). "The four regulatory regions include a CpG island located near the PHACTR1 migraine risk locus and three PREs located near the KCNK5, ASTN2, and RNF213 migraine risk locus." (PMID 32076896, 2020).
neurofibromatosis type 1 (5 papers, 2021 to 2025). A clinically heterogeneous, neurocutaneous genetic disorder characterized by cafe-au-lait spots, iris Lisch nodules, axillary and inguinal freckling, and multiple neurofibromas. "The two largest subgroups in our cohort consisted of RNF213 and neurofibromatosis type 1 (NF1) patients." (PMID 37012328, 2023). "RNF213 Arg4810Lys may also contribute to quasi-MMD onset in neurofibromatosis type 1 (NF1) patients." (PMID 40869185, 2025).
autoimmune disease (4 papers, 2016 to 2025). A disorder resulting from loss of function or tissue destruction of an organ or multiple organs, arising from humoral or cellular immune responses of the individual to their own tissue constituents. "Given its association with MMD and the described link between RNF213 and autoimmune diseases, we genotyped p.Arg4019Cys in MS patients and controls from Canada." (PMID 31170158, 2019). "Further experimental and epidemiological studies that focus on the link between infectious and autoimmune disease and RNF213 variants with low penetrance such as p.W4677L are needed." (PMID 27736983, 2016). "Two recent reports demonstrated that interferons overproduced under inflammatory conditions, such as infection and autoimmune disorders, induced highly up-regulated RNF213 in ECs." (PMID 27736983, 2016). "Within this context, RNF213 dysfunction may serve as a second or one of the multiple hits, along with autoimmune disorders, infections/inflammation, endothelial progenitor cells, and hemodynamic stress, which trigger MMV onset in a predisposed vascular milieu." (PMID 41001206, 2025). "In this study, we found that the RING finger protein 213 (RNF213) specifically promoted regulatory T (Treg) cell differentiation in CD4+ T cells and attenuated autoimmune disease development in an FOXO1-dependent manner." (PMID 39013878, 2024).
endothelial dysfunction (4 papers, 2021 to 2025). In vascular diseases, endothelial dysfunction is a systemic pathological state of the endothelium (the inner lining of blood vessels) and can be broadly defined as an imbalance between vasodilating and vasoconstricting substances produced by (or acting on) the endothelium. "In the case of pulmonary hypertension, RNF213 mutations have been implicated in abnormal vascular remodeling and endothelial dysfunction that contribute to a pathological increase in pulmonary arterial pressure and resistance." (PMID 40497951, 2025). "RNF213 plays important roles in vascular development, and mutant RNF213 has been shown to reduce angiogenesis and induce endothelial dysfunction." (PMID 33632238, 2021). "These lipid abnormalities aggravate oxidative stress and endothelial dysfunction, processes that may potentiate RNF213-mediated vascular injury." (PMID 40869987, 2025). "While not specific to RNF213, it may reduce microthrombosis and endothelial dysfunction." (PMID 40869987, 2025).
glioblastoma (4 papers, 2021 to 2024). The most malignant astrocytic tumor (WHO grade IV). "Due to its association with carcinogenesis, lower RNF213 expression was recently reported to decrease patient survival rates in glioblastoma cases." (PMID 36611871, 2022). "By affecting the MAPK/JNK signal pathway, RNF213 can inhibit the carcinogenesis of glioblastoma." (PMID 33763357, 2021).
Peripheral pulmonary artery stenosis (4 papers, 2022 to 2024). Stenosis of a peripheral branch of the pulmonary artery. "This concept was consistent with a report that the homozygous RNF213 p.Arg4810Lys variant was associated with intracranial and extracranial vasculopathy, including adulthood-onset peripheral pulmonary artery stenosis in segmental or subsegmental arteries." (PMID 35455046, 2022). "Finally, E3 ubiquitin-protein ligase RNF213 is a susceptibility allele for intracranial atherosclerosis, mutations of which are also associated with Moyamoa disease characterized by stenotic changes of the internal carotid arteries, peripheral pulmonary stenosis and pulmonary arterial hypertension." (PMID 35614104, 2022).
PHACE syndrome (4 papers, 2021 to 2025). PHACE is an acronym used to describe a syndrome characterized by the association of posterior fossa brain malformations, large facial haemangiomas, anatomical anomalies of the cerebral arteries, aortic coarctation and other cardiac anomalies, and eye abnormalities. "The association of RNF213 mutations with PHACE syndrome, which features a wide range of arterial anomalies affecting the aortic arch, cerebral vasculature, and cardiovascular structures, underscores the gene’s broad developmental influence." (PMID 40869987, 2025). "Rare RNF213 variants have also been identified in PHACE syndrome—a complex neurocristopathy characterized by infantile hemangiomas and diverse vascular malformations—as well as in cases of intracranial arterial dissection." (PMID 40869987, 2025).
Autoimmunity (3 papers, 2024 to 2025). The occurrence of an immune reaction against the organism's own cells or tissues. "Together, these results suggested that RNF213 deficiency in CD4+ T cells promoted autoimmunity by inhibiting immunosuppressive activity of Treg cells." (PMID 39013878, 2024). "Therefore, Rnf213 p.R4810K was considered a variant that exerts function with environmental factors, such as infection, autoimmunity, and inflammation, contributing to disease development." (PMID 40485582, 2025). "Overall, these results indicated that RNF213 might serve a critical role in autoimmunity through regulating the differentiation of CD4+ T cell subpopulations." (PMID 39013878, 2024). "Mouse RING finger protein 213 (RNF213), which possesses an AAA+ ATPase domain and an E3 ubiquitin ligase domain, is a giant E3 ubiquitin protein ligase consisting of 5,207 amino acids and is associated with autoimmunity, autophagy, angiogenesis and lipid metabolism." (PMID 40623121, 2025).
cerebral infarction (3 papers, 2019 to 2025). An ischemic condition of the brain, producing a persistent focal neurological deficit in the area of distribution of the cerebral arteries. "A landmark study investigating the pR4810k variant of RNF213 in 46,958 Japanese individuals (17,752 patients with cerebral infarction and 29,206 healthy controls) revealed a high risk of cerebral infarction, particularly large artery atherosclerosis." (PMID 39858606, 2025). "Among patients with MMD, the homozygous variant of RNF213 4810G > A was associated with an increased likelihood of onset at a younger age, cerebral infarction at diagnosis, and cognitive impairment during long-term follow-up." (PMID 32182997, 2020).
gastric cancer (3 papers, 2021 to 2026). A primary or metastatic malignant neoplasm involving the stomach. "The RNF213 gene is mutated in some malignant tumours, including gastric cancer, ovarian cancer, lung cancer, liver and bile duct cancer, yet there have been few functional studies on RNF213 mutations in malignancies." (PMID 41344988, 2026). "In a previous study, RNF213 mutations were identified in metastatic tumors and associated with tumorigenesis in various cancers (e.g., liver, ovarian, and gastric cancers)." (PMID 39338204, 2024). "It is mutated in some malignant tumors, such as ovarian cancer, gastric cancer and liver cancer, yet there have been few studies on RNF213 gene mutations in malignant tumors." (PMID 33200540, 2021).
infarction (3 papers, 2022 to 2025). A localised pathological necrosis of tissue resulting from obstruction of the blood supply usually by a thrombus, an embolus, or vascular torsion. "However, we found that patients carrying heterozygous mutations of RNF213 p.R4810K had a more severe pattern, such as infarction on presentation, more severe hemodynamic impairment, worse neurological status, and good post-operative Matsushima grade in our study." (PMID 35557620, 2022).
Insulin resistance (3 papers, 2023 to 2024). Increased resistance towards insulin, that is, diminished effectiveness of insulin in reducing blood glucose levels. "Interestingly, there is also confirmed evidence that the well-established susceptibility gene Ring Finger Protein 213 (RNF213) for MMD impacts cytotoxicity and insulin resistance." (PMID 38494486, 2024). "However, another report has shown that the relationship between MMD and obesity is associated with the expression of the ring finger protein 213 (RNF213) gene and is particularly affected via tumor necrosis factor-alpha-mediated inflammation and insulin resistance in adipocytes." (PMID 39600783, 2024). "In 2021, Sarkar and Thirumurugan demonstrated the regulation of RNF213 through the TNFα/PTP1B signaling pathway and PPARγ, suggesting that RNF213, similar to TNFα, may constitute an additional connection between MMA, inflammation, insulin resistance, and obesity." (PMID 37273690, 2023).
Listeria infection (3 papers, 2021 to 2024). "We show that NO production is reduced in macrophages from RNF213 KO mice, suggesting that RNF213 controls Listeria infection through regulation of DDAH1 transcription and production of NO." (PMID 34804992, 2021). "Taken together, our findings that depletion of RNF213 leads to reduced levels of DDAH1 and to lower levels of NO production suggest a potential mechanism by which RNF213 controls Listeria infection through regulation of DDAH1 transcription." (PMID 34804992, 2021). "Future work will assess which cell type is unable to control Listeria infection and whether RNF213 deletion also affects adaptive immune responses in addition to innate responses." (PMID 34599178, 2021). "Furthermore, RNF213 and ubiquitin colocalize on the bacterial surface suggesting that similar to its modification of Salmonella, RNF213 also acts as a ubiquitin E3 ligase during Listeria infection." (PMID 34599178, 2021). "Knockdown of RNF213 also results in downregulation of DDAH1, which we discover to exert antimicrobial activity against Listeria monocytogenes infection." (PMID 34804992, 2021).